SNORA21B (small nucleolar RNA, H/ACA box 21B)
Gene: Small nucleolar RNA gene on chromosome 17 (38,851,524 to 38,851,659, reverse strand). Ensembl gene ENSG00000252699.
Homologues: Orthologues: chimpanzee SNORA21B (99% identical), mouse Gm54825 (54% identical). Paralogues in human: SNORA21 (61% identical).